VDAC1 (voltage dependent anion channel 1)
Diseases named in the same sentence as VDAC1 in open-access papers (continued):
Sharing a sentence is not in itself a finding about the gene and the disease.
cancer (continued). "HKII has been shown to protect cancer cells from entering apoptosis by blocking the interaction of the pro-apoptotic protein Bax with VDAC1." (PMID 26322231, 2015). "The ATARiS gene-level score of dependency showed that knockout of Vdac1 decreased proliferation, even in human cancer cells driven by oncogenic K-Ras." (PMID 26322231, 2015). "The importance of VDAC1 in cancer cells is further reflected in the finding that silencing VDAC1 expression reduces cellular ATP levels and cellular growth." (PMID 26472185, 2015). "Transcriptome analysis of mouse embryonic fibroblasts (MEF) knocked out for Vdac1 highlighted alterations in not only cancer and inflammatory pathways but also in the activation of the hypoxia-inducible factor-1 (HIF-1) signaling pathway in normoxia." (PMID 26322231, 2015). "VDAC1 with a truncated C-terminus (VDAC1-ΔC) has been identified in both cancer cell lines and patient tumor tissue samples." (PMID 26090338, 2015). "Because VDAC-1 plays a key role in cancer cell fate through different signaling mechanisms, we investigated the expression pattern of VDAC1 and its interacting genes." (PMID 25333947, 2014). "Knockdown of VDAC-1 can lead to a block in cancer cell proliferation in nude mice subcutaneously injected with HeLa cancer cells." (PMID 25333947, 2014). "The complex of VDAC-1 and glycolytic enzyme hexokinase regulates metabolite trafficking through the outer membrane channels and provides cancer cells with metabolic advantages, which protects against mitochondria-mediated apoptosis." (PMID 25333947, 2014). "The complex of VDAC-1 and hexokinase regulates metabolite transportation through the outer membrane channels and provides cancer cells with metabolic advantages." (PMID 25333947, 2014). "VDAC1 is also overexpressed in cancer cells, and the binding of HK to VDAC1 on the outer mitochondrial membrane is a fundamental aspect of the aerobic glycolytic metabolism of cancer cells." (PMID 24648844, 2014). "The higher affinity of mitochondrial HK2 for glucose, ATP, and VDAC1 represents a high advantage for cancer cells survival and growth, conferring to them an aerobic glycolytic phenotype underlying the Warburg effect." (PMID 24648844, 2014). "We first explored the difference in expression level of VDAC1 between normal and tumor tissues in several human carcinomas." (PMID 25333947, 2014). "VDAC1 also contributes to the metabolic phenotype of cancer cells as reflected by its over-expression in many cancer types." (PMID 23506439, 2013). "Our findings show that cancer cells can be sensitized for chemotherapy induced cell death – at least in part – by NVP-BEZ235-mediated modulation of VDAC1." (PMID 24391739, 2013). "We offer here a working model to study the interactions of the OM pore forming VDAC1 with cytoplasmic proteins, an urgent task in basic and cancer-drug oriented research." (PMID 24324700, 2013). "As presented above (see VDAC Expression Levels in Cancers and Enhancement by Pro-apoptotic Drugs), the expression level of VDAC1 serves as a crucial factor in the process of mitochondria-mediated apoptosis as induced by various means." (PMID 23233904, 2012). "This claim is further supported by the findings that the ROS production and the anti-cancer activity of FNQs were increased upon VDAC1 over-expression and decreased upon silencing of VDAC1 expression by siRNA." (PMID 23233904, 2012). "In vitro and in vivo studies have shown that elevated levels of mitochondria-bound HK in cancer cells also protect against mitochondria-mediated apoptosis via direct interaction with VDAC1." (PMID 23233904, 2012). "This is reflected by VDAC1 over-expression in many cancer types, and by inhibition of tumor development upon silencing VDAC1 expression." (PMID 23233904, 2012). "The importance of VDAC1 for cancer cells is further reflected in the findings that silencing VDAC1 expression reduced cellular ATP levels and cell growth." (PMID 23233904, 2012).
cancer (continued). "As part of a system that impacts cell growth, the VDAC1–HK complex represents a remarkable target for cancer therapy (see The Interaction of VDAC1 with Hexokinase Regulates Cell Bioenergetics and Apoptosis)." (PMID 23233904, 2012). "VDAC1 also functions in ROS production and transport to the cytosol, with elevated ROS generation being seen in cancer cells." (PMID 23233904, 2012). "Here, we review current evidence pointing to the function of VDAC1 in cell life and death, and highlight these functions in relation to cancer." (PMID 23233904, 2012). "These functions, together with VDAC1 being over-expressed in some cancer cells, point to VDAC1 as being a rational target for the development of a new generation of therapeutics." (PMID 23233904, 2012). "VDAC1 is integral to mitochondrial ATP production as a metabolite transporter, as the docking site for mitochondrial-bound HK, and is highly expressed in cancers." (PMID 23233904, 2012). "The anti-cancer activity of furanonaphthoquinones (FNQs) was increased upon VDAC1 over-expression and decreased upon silencing of VDAC1 expression by siRNA." (PMID 23233904, 2012). "A link between the VDAC1 C-terminal region and cancer also comes from studies connecting hypoxia and C-terminal cleavage." (PMID 23233904, 2012). "Thus, metformin, by inhibiting HK activity and inducing its detachment from VDAC1, results in both inhibiting cancer cell metabolism and inducing apoptosis." (PMID 40430574, 2025). "The co-culture experiment indicates that Schwann cells may facilitate cancer progression through upregulation of VDAC1." (PMID 40052442, 2025). "Moreover, HK2 contributes to apoptosis evasion in cancer cells by binding to VDAC1 and competing with Bax." (PMID 40941984, 2025). "Schwann cells may facilitate cancer progression through upregulation of VDAC1, which is primarily expressed in cancer cells." (PMID 40052442, 2025). "Given that interactions between nervous system and cancer cells can promote cancer progression, we hypothesized that patients with co-high expression of notable interactions (APOD_VDAC1, APOD_PDZK1IP1, and CLDN4_APOD) would have poor prognosis." (PMID 40052442, 2025). "Moreover, VDAC1 is overexpressed in many types of cancers, underscoring to its central role in the pathophysiology of the disease." (PMID 39921338, 2025). "Notably, TRPV2 is implicated in inducing the death of various cancer cell types; however, many studies also indicate that the action of CBD is also mediated by the receptors TRPV1, TRPV4, CB1, CB2, and VDAC1." (PMID 40006844, 2025). "Thus, VDAC1 is a key regulator of metabolic and energy reprogramming that disrupts cancer energy and metabolism homeostasis by downregulating VDAC1, making it a potential anti-cancer therapy strategy." (PMID 39272828, 2024). "We have demonstrated that both siRNA against VDAC1 and VDAC1-based peptides are effective in inhibiting tumor growth in several cancer models, were the si-hVDAC1 encapsulated in PLGA-PEI nanoparticles, crossed the blood–brain barrier (BBB) and reached tumors in the brain." (PMID 39272828, 2024). "Downregulation of VDAC1 expression is anticipated to affect cancer cell growth." (PMID 39456237, 2024). "We further investigated whether VDAC1 oligomerization is involved in cysteine deprivation-induced ferroptosis in other cancer cell types." (PMID 39521767, 2024). "Research has shown that VDAC1 is highly expressed in cancer cells." (PMID 38989148, 2024). "In cancer cells, VDAC1 overexpression supports increased metabolite and energy supply." (PMID 39456237, 2024). "However, cancer cells also overexpress anti-apoptotic proteins to counteract VDAC1-mediated cell death." (PMID 39456237, 2024).
cancer (continued). "Our finding that the expression levels of KRT-14, SOX2, CD44, and ALDH1a decreased upon si-m/hVDAC1-B BC treatment suggests that the metabolic reprogramming of cancer cells via VDAC1 depletion reduces CSC markers, suggesting the inhibition of their proliferation and/or induction of differentiation." (PMID 38607066, 2024). "However, in cancer, this pro-apoptotic effect is countered by the overexpression of anti-apoptotic proteins such as Bcl-2, Bcl-xL, and HK, which interact with VDAC1." (PMID 39456237, 2024). "Indeed, using a xenograft mouse model of human-derived SCLC H69 cells, si-m/hVDAC1-B inhibited tumor growth and reduced the expression of VDAC1 and energy- and metabolism-related enzymes, and of cancer stem cells in the established xenograft." (PMID 39272828, 2024). "Cancer cells employ various strategies to avoid apoptosis, including the overexpression of anti-apoptotic proteins such as members of the Bcl-2 family and HK, and VDAC1 binds HK, Bcl-2, and Bcl-xL." (PMID 39334905, 2024). "si-VDAC1 treatment of several tumor types induces metabolic rewiring of the malignant phenotype of cancer metabolism, resulting in a reversal of oncogenic properties that include reduced tumor growth, invasivity, stemness, epithelial–mesenchymal transition (EMT), and angiogenesis." (PMID 38607066, 2024). "Thus, this review underscores the potential of targeting VDAC1 as a strategy for addressing high-energy-demand cancers." (PMID 39456237, 2024). "Such metabolic re-programming in cancer cells also includes a marked overexpression of VDAC1." (PMID 39334905, 2024). "Thus, VDAC1-based peptides targeting the anti-apoptotic proteins provide an opportunity to develop new anti-cancer therapies that allow the chemo resistance of cancer cells to be overcome." (PMID 39334905, 2024). "Furthermore, silencing VDAC1 in cancer cells impacted the expression of structural proteins, matrix metalloproteinases, and lysyl oxidase (Lox), triggering a stromal response similar to that observed during wound healing." (PMID 39456237, 2024). "It was demonstrated that silencing VDAC1 expression inhibited cancer cell proliferation." (PMID 37046443, 2023). "VDAC1 is overexpressed in many cancer types, and silencing VDAC1 inhibits tumor development." (PMID 38067169, 2023). "By contrast, the VDAC1 level was lower in OSCC cancer tissues than in normal tissues." (PMID 37198593, 2023). "The VDAC1′s involvement in cell death or survival indicates that this protein might be a prime regulator target for treating cancer." (PMID 37046443, 2023). "In many cancers, the interaction of VDAC1 with hexokinase (HK) converts glucose to glucose-6-phosphate through phosphorylation, which initiates glycolysis, contributes to the unhindered growth of cancer cells, and inhibits apoptosis." (PMID 36418670, 2023). "In most cancer cells, when VDAC1 is activated, both types of apoptosis pathways are triggered." (PMID 37160920, 2023). "Here, we present the pro-apoptotic activity of the hydroethanolic extracts from the indicated three plants while deciphering their mode of pro-apoptotic, anti-cancer activity involving mitochondria-mediated apoptosis and the mitochondrial gatekeeper protein, the voltage-dependent channel 1 (VDAC1)." (PMID 36900417, 2023). "Down-regulation of VDAC1 decreases calcium uptake by the mitochondria in cancer cell lines as in the human cervix and in the colon, and diminishes the activation of the mitochondrial intrinsic apoptosis pathway, consequently promoting cancer cell survival and tumor metastasis." (PMID 37046443, 2023). "Furthermore, HKII is involved in the apoptosis inhibition of cancer cells since it can anchor to voltage-gated anion channel 1 (VDAC1) in the mitochondrial outer membrane (MOM) to exchange ADP for ATP in the mitochondria." (PMID 37569780, 2023).
cancer (continued). "Given the pro-apoptotic role of VDAC1 protein, in this pathological context a reduced expression could be compatible with the increased cell resistance to apoptosis typical of cancer phenotype." (PMID 37344914, 2023). "Additionally, a series of subgroup analyses were performed by distinct clinical factors and demonstrated the detailed correlation between expression levels of VDAC1 and selected cancer types." (PMID 35958281, 2022). "Cancer cells typically possess high antiapoptotic proteins, which may require more VDAC1 in the outer mitochondrion membrane to provide more anchor points." (PMID 35958281, 2022). "Thus, VDAC1 transcriptional activity increased in cancer cells and responded more quickly to nutrient starvation." (PMID 35972052, 2022). "Moreover, we conducted a signal pathway enrichment analysis based on VDAC1 interacting proteins and VDAC1 expression-related genes to further study the molecular mechanism of the VDAC1 gene in cancer progression." (PMID 35958281, 2022). "Furthermore, the results demonstrate that silencing VDAC1 expression leads to metabolic reprogramming of cancer cells, resulting in an altered tumor microenvironment and reduced inflammation, elimination of cancer stem cells, and induced differentiation." (PMID 35883451, 2022). "This study analyzed VDAC1 in pan-cancer using the TCGA program and GEO database for the first time." (PMID 35958281, 2022). "The results showed a negative correlation between VDAC1 expression and the estimated infiltration value of cancer-associated fibroblasts in BLCA, COAD, and KIRC, but a positive association with TGCT." (PMID 35958281, 2022). "Moreover, we demonstrated that VDAC1 represents an intersection between metabolism and cancer biology, with metabolism reprogramming following VDAC1 silencing not only inhibiting cell proliferation, but also directing the cell toward a differentiated state." (PMID 35883451, 2022). "Furthermore, targeted drugs acting on VDAC1 against tumor growth and proliferation was a promising strategy for the treatment of cancer." (PMID 35109855, 2022). "The overexpressed VDAC1 in the cancer cells can interact with hexokinase (HK), a rate-limiting enzyme of glycolysis, and then promote mitochondrial ATP to coupling to glucose, which contributes to cancer cell metabolism." (PMID 35729567, 2022). "The TIMER2 approach was applied to analyze VDAC1 expression in various cancer types of TCGA." (PMID 35958281, 2022). "VDAC1 also regulates apoptosis via interactions with apoptosis regulatory proteins, such as hexokinase (HK), B-cell lymphoma 2 (Bcl-2), and B-cell lymphoma-extra-large (Bcl-xL), some of which are highly expressed in many cancers." (PMID 36291596, 2022). "The observation that VDAC1 was overexpressed in a variety of tumors showed that VDAC1 may be essential for cancer cell survival." (PMID 35109855, 2022). "Besides, by inhibiting the expression of MCL-1, an anti-apoptotic protein, and VDAC1/2 that is essential for the release of cytochrome C from mitochondria to the cytoplasm, miR-29a promoted apoptosis in cancer cells." (PMID 36140219, 2022). "Finally, tumor VDAC1 silencing also eliminated cancer stem cells and induced cell differentiation to normal-like cells." (PMID 35883451, 2022). "VDAC1 is regarded as a potential target for anti-cancer therapy." (PMID 36042412, 2022). "In cancers, VDAC1 is overexpressed, while its oligomerization and, thereby, apoptosis are prevented by the overexpression of anti-apoptotic proteins such as hexokinase and Bcl2, and their detachment from VDAC1 leads to VDAC1 oligomerization and apoptosis." (PMID 36578022, 2022). "Accumulating studies have proved that abrogation of VDAC1 expression significantly inhibited tumor growth in cancers, suggesting that VDAC1 may be a novel therapeutic target." (PMID 35109855, 2022).
cancer (continued). "Along with regulating cellular energy and metabolism, VDAC1 is involved in mitochondria-mediated apoptosis, participating in the release of apoptotic proteins, and interacting with the anti-apoptotic proteins, Bcl2 and Bcl-xL, and HK, overexpressed in cancers." (PMID 34671273, 2021). "These conflicting consequences demonstrate the differential effects of VDAC1 expression in different kinds of cancer and may need further exploration." (PMID 33680287, 2021). "Thus, metformin inhibits HK activity and induces HK detachment from the VDAC1, resulting in both inhibiting cancer cell metabolism and inducing apoptosis." (PMID 34671273, 2021). "Thus, VDAC1 depletion using si-VDAC1 represents therapeutic potential, inhibiting cancer cell proliferation and also inducing the modulation of TME components, which influences cancer progression, migration, and invasion." (PMID 34200480, 2021). "Compared with normal cell lines, the expression of VDAC1 increases in much human cancer cell lines." (PMID 34579758, 2021). "Thus, we propose that attacking cancer cell metabolism via VDAC1 down expression reduces the cancer wound healing process associated with inflammatory and stromal activities related to the attenuation of the immune response." (PMID 34200480, 2021). "HK2 binds to VDAC1 in the mitochondria to prevent apoptosis in cancer cells." (PMID 33802591, 2021). "It is now clear that VDAC1 is the main target against cancer." (PMID 34579758, 2021). "Furthermore, VDAC1 has also been reported to promote tumor growth and play a controversial role in the prognosis of different cancers." (PMID 33680287, 2021). "In cancer, metformin detaches HK from VDAC1, allowing apoptosis, and in neurodegenerative diseases, it interferes with HK phosphorylation and, thereby, allows its bind to VDAC1, protecting against cell death." (PMID 34671273, 2021). "Moreover, the up-regulation of the VDAC-1 increases the expression of apoptotic proteins such as hexokinase (HK), B-cell lymphoma-xL (Bcl-xL) and Bcl-2 in cancer cells and leads to the growth inhibition of such cells." (PMID 33536086, 2021). "It has been shown that depletion of VDAC1 led to inhibition of tumour development and growth of cancer cells in both in vitro and in vivo models of breast, lung and glioblastoma, as well as and induction of metabolic rewiring reversing the oncogenic properties of cancer cells." (PMID 33069104, 2021). "Cytc release from mitochondria is the driving force for apoptosome leading to apoptotic cell death in several malignant tumor, and VDAC1 has been widely reported to be interacted with pro- or antiapoptotic proteins such as Bcl-2 and HK, whereby mediating the release of Cytc." (PMID 33680287, 2021). "Thus, the effects of VDAC1 silencing on the link between cancer cell metabolism and the immune system and the ability of tumors to create an immunosuppressive microenvironment are a topic for another study." (PMID 34200480, 2021). "Thus, the anti-cancer effects of metformin can be mediated through induction of VDAC1 overexpression and thereby apoptosis, affecting cell metabolism and/or Ca2+ homeostasis." (PMID 34671273, 2021). "We show that metabolic rewiring upon mitochondrial VDAC1 silencing in cancer cells affected several components of the TME, such as structural protein matrix metalloproteinases and Lox, and elicited a stromal response resembling the reaction to a foreign body in wound healing." (PMID 34200480, 2021). "In HepG2 cancer cells, VDAC1/2/3 knockdown reduces the potential of the mitochondrial membrane." (PMID 33804985, 2021). "Alternatively, modulating VDAC1 to activate apoptosis could be a possible therapeutic strategy for cancer." (PMID 33114780, 2020). "Previous studies reported that in cancer cells, overexpression of HK by transfection with recombinant HK cDNA, protected cells against apoptotic cell death via increased interaction between HK and VDAC1." (PMID 32901466, 2020).